VIM (vimentin)
Diseases named in the same sentence as VIM in open-access papers (continued):
Sharing a sentence is not in itself a finding about the gene and the disease.
gastric cancer (246 papers, 2006 to 2026). A primary or metastatic malignant neoplasm involving the stomach. "This shift in macrophage polarization resulted in decreased expression of the migration-associated proteins N-cadherin and vimentin, while increasing E-cadherin levels, thereby inhibiting gastric cancer cell migration." (PMID 40765835, 2025). "Overexpression of vimentin has been associated with various malignancies, such as lung and gastric cancers, where it is associated with increased metastatic potential, higher nuclear grade, and poorer overall survival outcomes." (PMID 40666093, 2025). "The expression of vimentin in cancerous events can also serve as a prognostic marker, for example in gastric cancer where the overexpression of vimentin is linked to metastasis." (PMID 37475865, 2023). "Some of the proposed genes have also been implicated in other cancers, for example gastric cancer (vimentin), large B-cell lymphoma (nucleolin), and pancreatic cancer (NAP1L1)." (PMID 33187334, 2020). "Gastric cancer is also associated with vimentin overexpression, and as vimentin is correlated to metastasis formation, it has been suggested to be an indicator of prognosis." (PMID 30248895, 2018). "Loss of E-cadherin expression and aberrant expression of vimentin and the known gastric cancer stem cell maker CD44 were significantly associated with aggressive clinicopathologic features." (PMID 25441488, 2014). "Therefore, vimentin+CAFs are an independent prognostic factor, and associated with recurrence, distant metastasis and reduced survival in patients with gastric cancer." (PMID 37143134, 2023). "Therefore the CORO1C–cyclin D1–vimentin pathway is in turn associated with the prognosis of gastric cancer patients." (PMID 30974047, 2019). "Collectively, our data show that circNHSL1 acts as an oncogenic gene in gastric cancer progression through miR-1306-3p/SIX1/Vimentin axis, and may serve as a novel diagnostic marker and target for treatment of gastric cancer patients." (PMID 31438963, 2019). "CircNHSL1 promotes gastric cancer progression through miR-1306-3p/SIX1/Vimentin axis, and may serve as a novel diagnostic marker and target for treatment of gastric cancer patients." (PMID 31438963, 2019). "Thus, loss of expression of epithelial proteins such as E-cadherin and acquisition of mesenchymal proteins, such as N-cadherin and vimentin, associates with advanced stage and poor outcome in gastric carcinomas." (PMID 27409173, 2016). "Cyclin D1 and vimentin might mediate the oncogenicity in human gastric cancer caused by CORO1C." (PMID 30974047, 2019). "Western blotting experiments revealed a marked increase in the expression of N-cadherin and vimentin, suggesting that M2 macrophages induced by exosomes derived from gastric cancer promote the migration of gastric cancer cells by facilitating the EMT process." (PMID 40612677, 2025). "qRT-PCR analysis revealed that both ACTA2 and VIM were significantly upregulated in gastric cancer tissues compared to adjacent normal tissues (p < 0.01)." (PMID 40677704, 2025). "Western-blotting was used to detect the protein expression of EMT/ metastasis related markers MMP-2, MMP-9, N-cadherin, Zeb1, Vimentin, Snail and E-cadherin in gastric cancer cells." (PMID 40265472, 2025). "While this study was conducted in PDAC cells, the downstream effects of BAR502—particularly LIFR antagonism and vimentin downregulation—are also relevant in gastric cancer (GC)." (PMID 41163398, 2025). "As an epithelial-derived neoplasm, undifferentiated gastric carcinoma typically expresses epithelial markers and generally lacks or rarely exhibits expression of mesenchymal markers (e.g., Vimentin)." (PMID 41170461, 2025). "Immunofluorescence staining was used to measure the levels of E-cadherin (an epithelial cell marker) and vimentin (a mesenchymal cell marker) in three gastric cancer cell lines." (PMID 39247186, 2024).
gastric cancer (continued). "Clearly, the activation of EMT, especially through the upregulation of N-cadherin, Vimentin and Fibronectin by the suppression of miR-598-3p, have been shown to make a great contribution to gastric cancer metastasis in vitro and in vivo." (PMID 38491378, 2024). "We also detected changes in PGK1, PI3K, AKT, vimentin and related phosphorylation levels in gastric cancer cells after coculturing circGLIS3-knockdown exosomes and NC exosomes." (PMID 38459513, 2024). "In gastric cancer, strong immunoreactivity of vimentin is detected only in stroma cells, most of which are CAFs." (PMID 37143134, 2023). "The results showed that cigarette smoke-treated exosomes from gastric cancer cells promoted the expression of Vimentin and N-cadherin and inhibited the expression of E-cadherin." (PMID 37235279, 2023). "HE staining and vimentin IHC further confirmed the effect of LINC00240 expression on metastasis of gastric cancer cells in vivo." (PMID 37072811, 2023). "Luteolin application caused a reversion of EMT via shrinkage in the cytoskeleton and increment in the expression of epithelial biomarker E-cadherin and downregulation of the mesenchymal biomarkers N-cadherin, vimentin, and Snail in gastric cancer cells." (PMID 36992138, 2023). "UMAP revealed eight distinct clusters, two CD45 positive immune cell populations and five vimentin positive populations whose expression is more correlated with the invasive phenotype of gastric cancer." (PMID 37833290, 2023). "Meanwhile, SIX1 directly binds to vimentin promoter to further enhance vimentin expression This result suggested that CircNHSL1 promoted gastric cancer progression through the miR-1306-3p/SIX1/Vimentin axis." (PMID 36750914, 2023). "Immunohistochemistry results showed that GLUT3, N-cad, and vimentin levels were significantly higher in gastric cancer tissues (n = 7) than in normal gastric tissues (n = 7), whereas E-cad levels exhibited the opposite pattern." (PMID 38041125, 2023). "DOP suppressed the migration of gastric cancer cells by decreasing the protein expression of N-cadherin and Vimentin and increasing E-cadherin." (PMID 37894541, 2023). "Downregulation of FBXO2 decreased EMT in gastric cancer cells, increased E-cadherin expression, and decreased N-cadherin and vimentin expression." (PMID 37033662, 2023). "The WB analyses indicated that the levels of N-cadherin and vimentin were lower in the PA-treated human gastric cancer cells than in the BSA-treated cells, and the decreases occurred after treatment with 75–150 μM of PA for 24 h or 150 μM of PA for 12–24 h." (PMID 36672337, 2023). "In gastric cancer, miR-27 increases the expression level of the EMT-associated genes ZEB1, ZEB2, SLUG, and Vimentin, and decreases E-cadherin." (PMID 38002286, 2023). "CM-DOP inhibited migration by reducing the expression of N-cadherin and vimentin, increasing E-cadherin, and promoting apoptosis through upregulating Caspase-3 and increasing the ratio of Bax/Bcl-2 on gastric cancer cells." (PMID 37894541, 2023). "SMARCA4 promotes gastric cancer metastasis by suppressing E-cadherin expression and increasing vimentin expression." (PMID 36902184, 2023). "Overexpression of CD14 and ILK1 impacted the colony formation ability of gastric cancer and increased expression of Vimentin." (PMID 37568802, 2023). "In general, it was found that Luteolin exerted its biological properties by inhibiting Cyclin D1, Cyclin E, Bcl2, MMP-2, MMP-9, N-cadherin, Vimentin, and inducing p21, Bax, and E-Cadherin expressions in gastric cancer cells." (PMID 36992138, 2023). "For example, the study found that the coexpression of FOXK1 and Vimentin enhanced cell metastasis through the induction of EMT in gastric cancer cells." (PMID 35281866, 2022). "In this study, we identified that overexpression of Flotillin-1 decreased the epithelial marker E-cadherin and upregulated mesenchymal markers such as N-cadherin, Vimentin and Snail in gastric cancer cells." (PMID 35990908, 2022).
gastric cancer (continued). "FoxK1 can physically interact with and stabilize vimentin, and FoxK1 positively correlates with vimentin expression in gastric cancer cells." (PMID 35903069, 2022). "E-cadherin was upregulated, and N-cadherin, Vimentin and Snail were decreased in Flotillin-1-knockdown gastric cancer cells." (PMID 35990908, 2022). "The immunohistochemical results showed that GWH extracts inhibited the expression of Ki67 and Vimentin and up-regulated the expression of E-cadherin to inhibit the growth, invasion, and migration of gastric cancer cells." (PMID 35281866, 2022). "In a similar fashion, Han and coworkers reported that TSA treatment induces mesenchymal-like morphological modifications BGC-823 human gastric cancer and increases the expression rate of the mesenchymal markers vimentin and twist." (PMID 36297347, 2022). "Our results are in agreement with previous works showing that, in gastric cancers, LC3B expression is correlated with the expression of the EMT marker vimentin, and associated with poor clinical outcomes." (PMID 34681055, 2021). "By analyzing the DNA methylation data of TCGA gastric cancer database, there were 12 DNA methylation sites in VIM, 8 in CDH1, 3 in S100A4, 7 in EPCAM, and 6 in VCL." (PMID 33535187, 2021). "For instance, in gastric cancer, LINC00675 was found to be downregulated in cancer tissues and inhibit metastasis through associating with vimentin and enhancing its phosphorylation." (PMID 34738869, 2021). "Similar to the results of in vitro, we also found mJPYZ increased the protein expression levels of E-cadherin and decreased the levels of N-cadherin, Vimentin, which indicated that mJPYZ inhibited gastric cancer growth and EMT in the xenograft tumor." (PMID 34926270, 2021). "The expression level of VIM was also significantly up-regulated in the gastric cancer tissues of patients from our medical center, while the expression levels of the other three genes did not change significantly." (PMID 33535187, 2021). "There were significantly higher Vimentin and β-catenin levels in gastric cancer compared to normal tissues." (PMID 35003354, 2021). "What’s more, phosphor-ERK, MMP2/9, N-cadherin, Vimentin, Snail, Slug and Twist1 were downregulated and E-cadherin was upregulated in gastric cancer cells upon exposure to PD98059 at 0, 5, 10, 20 μM for 24 h." (PMID 34588421, 2021). "Administration of Wnt/β-catenin pathway agonist can promote the proliferation and migration of gastric cancer cells, reduce the levels of N-cadherin, Vimentin, and β-catenin proteins, and increase the levels of E-cadherin proteins." (PMID 35003354, 2021). "It has been reported that high vimentin and reduced E-cadherin expression is an important predictor in various types of cancers, such as gastric cancer, colorectal cancer and pancreatic cancer." (PMID 33789624, 2021). "In this study, AGS gastric cancer cells were treated with metformin and vimentin-specific siRNA (vim-siRNA) for 48 h." (PMID 35178358, 2021). "The immunohistochemical analysis outcomes demonstrated that HGF derived from GCMSCs upregulated Vimentin and downregulated E-cadherin in gastric cancer tissues." (PMID 33718248, 2021). "Immunofluorescence results confirmed the co-localization of ADAR1 with CALR, E-cadherin, Vimentin, and β-catenin proteins in normal and gastric cancer tissue samples." (PMID 35003354, 2021). "For instance, FOXK1 interacts with and stabilises vimentin, thereby promoting gastric cancer cell migration and metastasis via the induction of EMT." (PMID 33757532, 2021). "In gastric cancer, vimentin often plays a role in the invasive phenotype and as a prognostic marker of gastric cancer." (PMID 32670437, 2020). "Increased vimentin expression has been reported in various cancers, such as prostate cancer, gastric cancer, and esophageal squamous cell carcinoma, and correlates with tumor growth, invasion, migration, and poor prognosis." (PMID 32850341, 2020).
gastric cancer (continued). "In the current study, we found that silencing of GPER1 inhibited the EMT by upregulating E-cadherin and downregulating N-cadherin and vimentin, resulting in a decline in the migration and invasion of gastric cancer cell lines." (PMID 33425895, 2020). "It has been demonstrated that vimentin promoter methylation inversely correlates with vimentin expression and disease progression in gastric cancer." (PMID 31940801, 2020). "PKM2 siRNA significantly increased expression of E-cadherin and decreased expression of N-cadherin and vimentin, compared with the control group (p < 0.05), in the human gastric carcinoma cell lines MKN-45 and SGC-7901." (PMID 33376737, 2020). "For all gastric cancer cases, our results showed that high ERBB2 expression was associated with the worse overall survival of GC patients, VIM, IFI44, IFIT2, and MX1 showed similar associations (P < 0.05)." (PMID 31949544, 2019). "In gastric cancer cells, the miR-30a based inhibition of VIM is induced by tumor suppressor RUNX3 transcription factor, in addition, decreased miR-30a level enhance invasion ability of cells." (PMID 31752264, 2019). "Consistently, immunoblot analysis revealed a significant difference between the protein expression levels of EpCAM and vimentin in both gastric cancer cell lines and fibroblasts." (PMID 31850215, 2019). "Fluorescence intensity analysis showed that all five gastric cancer cell lines were marked by global expression levels of EpCAM, while normal fibroblasts exhibited up-regulation of vimentin expression." (PMID 31850215, 2019). "Western blot showed that E-cadherin expression was decreased and of N-cadherin, Vimentin, and Snail were increased in gastric cancer cells, which downregulated UFM1 expression." (PMID 31533855, 2019). "For HER2+ gastric cancer, the high expression of VIM, IFI44, IFI44L, IFIT2, IFIT3, ISG15, OAS1, or OASL was associated with worse overall survival (P < 0.05)." (PMID 31949544, 2019). "Pearson correlation analysis showed that the mRNA expression level of SIX1 was positively correlated with that of Vimentin in above 61 paired gastric cancer tissues (p < 0.05)." (PMID 31438963, 2019). "To further investigate the molecular mechanism by which 28-hydroxy-3-oxoolean-12-en-29-oic acid inhibits the invasion and metastasis of SGC-7901 and BGC-823 gastric cancer cells, we also examined the levels of E-cadherin, N-cadherin and vimentin." (PMID 31569766, 2019). "Gastric cancer cell-lines and PDCs were subjected to multi-color immunofluorescence analysis against EpCAM and vimentin to evaluate the tumor cell index based on EpCAM expression levels." (PMID 31850215, 2019). "DAPT has been shown to inhibit cell proliferation, migration, and invasion of gastric cancer by inhibiting the Notch1/Hes1 pathway, and in line with the study results, decreased expression of mesenchymal markers such as vimentin and Snail in gastric cancer." (PMID 31508369, 2019). "Using an immunofluorescence-based approach, we employed numerous gastric cancer cell lines and PDCs to assess tumor cell populations within each given tumor by analyzing the intensity of EpCAM and vimentin expression." (PMID 31850215, 2019). "To summary, SIX1 promotes gastric cancer progression by positively regulating Vimentin expression in the transcriptional level." (PMID 31438963, 2019). "Our findings indicate that DSGOST treatment regulates EMT by reducing E-cadherin and increasing of mesenchymal markers including N-cadherin and vimentin in gastric cancer cells." (PMID 29844404, 2018). "In this study, we found that TIPE1 inhibits EMT as demonstrated by the significant up‐regulation of E‐cadherin expression and downregulation of vimentin and transcription factors in gastric cancer cells." (PMID 28994231, 2018).
gastric cancer (continued). "More importantly, SPOCK1 expression was found to be related with E‐cadherin, Slug and Vimentin expressions [P < 0.001, Contingency coefficient (C) = 0.431; P = 0.015, C = 0.234; P = 0.005, C = 0.271] in gastric cancer tissues." (PMID 28940639, 2018). "Mechanistically, TSP50 activates EMT in gastric cancer by up-regulating Vimentin and Twist whereas down-regulating E-Cadherin." (PMID 29361914, 2018). "A clinicopathological association study of the 102 patients with gastric cancer demonstrated that the expressions of SPOCK1, E‐cadherin, Slug and Vimentin significantly correlated with T stage, pTNM stage and lymph node metastasis, respectively (P < 0.05)." (PMID 28940639, 2018). "We found that PAX8-overexpressing gastric cancer cells displayed an upregulation of E-cadherin and downregulation of vimentin." (PMID 30021604, 2018). "SPOCK1, Slug and Vimentin shared markedly higher expression in gastric cancer tissues, compared with those in adjacent normal gastric mucosas (P = 0.001, P = 0.017 and P = 0.001, respectively)." (PMID 28940639, 2018). "UBE2T knock-down increased E-Cadherin and β-Catenin expression and decreased Fibronectin and Vimentin expression, and these changes in expression likely inhibited metastasis and invasion in gastric cancer cells." (PMID 28427240, 2017). "This has been reported in a cohort of 178 patients with gastric cancer, where CD68‐positive cell density is associated with the expression of EMT features in cancer cells (E‐cadherin loss and vimentin de novo expression)." (PMID 28599100, 2017). "For UCA1, pieces of evidence also documented that ectopic expression of UCA1 boosted cell migration and invasion via activating the vimentin and snail expression, and suppressed E-cadherin and zonula occludens-1 protein levels in gastric cancer." (PMID 29221199, 2017). "The essential role of upregulated vimentin in invasion of gastric cancer shows the importance of our finding in vimentin suppression by metformin." (PMID 28334027, 2017). "In this study, we found that critical molecular markers of EMT were affected by miR-93, and the expression of mesenchyme cell marker N-cadherin and Vimentin were upregulated, while the epithelia marker E-cadherin was downregulated in gastric cancer cells." (PMID 29220395, 2017). "In this study, we found that vimentin was highly expressed in human gastric cancer (GC) tissues and cell lines and significantly promoted cell growth, migration and invasion." (PMID 27448976, 2017). "To address this question, we detected the expression of E-cadherin, N-cadherin and Vimentin mRNA in gastric cancer tissues by qRT-PCR." (PMID 29220395, 2017). "High vimentin expression and low E-cadherin expression are observed in various epithelial cancers, including gastric cancer, and are correlated with EMT, tumor growth, invasion, and poor prognosis." (PMID 26871290, 2016). "Gal-1 expression was negatively associated with E-cadherin expression but positively correlated with vimentin expression in gastric cancer." (PMID 27835885, 2016). "We assessed the expression of Gal-1, E-cadherin and vimentin in metastatic lymph nodes from 97 patients with gastric cancer using immunostaining." (PMID 27835885, 2016). "E-cadherin is inhibited and N-cadherin is activated during EMT in gastric cancer, and the expression levels of the cytoskeletal protein markers β-catenin and Vimentin are also increased." (PMID 27102302, 2016). "Immunohistochemistry assay revealed that the protein expression of GFAT1 was positively correlated with E-cadherin staining and negatively associated with the levels of N-cadherin, Vimentin, Snail as well as TGF-β1 in our cohort of gastric cancer samples." (PMID 27509259, 2016). "The results of western blot revealed that the fused cells exhibited an obvious decrease in E-cadherin expression while increase in the expression of vimentin and N-cadherin compared to their parental gastric cancer cells." (PMID 26498753, 2015).